INS (insulin)
Diseases named in the same sentence as INS in open-access papers (continued):
Sharing a sentence is not in itself a finding about the gene and the disease.
metabolic syndrome (continued). "It is known that metabolic syndrome is closely related to insulin signaling, oxidative stress, inflammation, and atherosclerosis." (PMID 28367174, 2017). "Numerous studies have revealed the pharmaceutical importance of FGF21 for treating metabolic syndrome, which is due to its strong insulin-sensitizing and thermogenic effects on adipose tissues." (PMID 28129657, 2017). "Enhanced differentiation of fibroblast-like pre-adipocytes into mature adipocytes by the use of compounds mimicking insulin functions or enhancing insulin sensitivity provides a novel strategy for controlling the complications of metabolic syndrome." (PMID 28972997, 2017). "The PPARG gene plays an important role in adipocytes differentiation, insulin sensitivity regulation, and its variation has been reported association with some CAD related risk factors, such as T2DM or metabolic syndrome (MS)." (PMID 28415751, 2017). "†Incomplete data for metabolic syndrome for 35 participants (Insulin sensitive: n = 25; Insulin resistant: n = 10)." (PMID 29123160, 2017). "Chronic hyperinsulinemia is a phase of the development of metabolic syndrome (MS) during which systemic levels of insulin are elevated." (PMID 29430572, 2017). "In the context of the metabolic syndrome, a first human trial on obese Caucasian male subjects showed an increase in peripheral insulin sensitivity in patients receiving allogenic gut microbiota, as well as a tendency to increased hepatic insulin sensitivity." (PMID 29056925, 2017). "Resistance to the actions of insulin on glucose and carbohydrate metabolism will give rise to the classical features of metabolic syndrome." (PMID 28451029, 2017). "Blood samples were then collected and analyzed for fasting serum concentration of lipid components of metabolic syndrome, insulin, serum complement C3 and High sensitivity C reactive protein (hsCRP)." (PMID 29299442, 2017). "Metabolic syndrome, a concurrence of disturbed glucose and insulin metabolism, overweight and abdominal fat distribution, dyslipidemia, and hypertension, is associated with subsequent development of type 2 diabetes mellitus and cardiovascular disease." (PMID 26893942, 2016). "Our results suggest that a low-iron diet reduce the dyslipidemia, and improve insulin and glucose tolerance in healthy rats." (PMID 27064411, 2016). "APP alone improved dyslipidemia and glucose intolerance by potentiating glucose-stimulated insulin secretion as much as APP + LJH + GJE in OVX rats." (PMID 27216600, 2016). "Upon initiation of WD SW, the mice gained weight, became insulin resistant and developed dyslipidemia." (PMID 27261415, 2016). "The prevalence of risk factors was higher in insulin, meglitinides and TZD group than in sulfonylureas group, including HTN and dyslipidemia." (PMID 27513562, 2016). "In this large cross-sectional study of community-dwelling older men, higher levels of MVPA and lower levels of SB were associated with better metabolic health in terms of WC, BMI, FMI, insulin level and metabolic syndrome." (PMID 26980183, 2016). "It has been found that rice bran derivatives reduce plasma and liver lipids, whereas protein hydrolysates from rice bran improve insulin and leptin sensitivity in high-fat diet-induced metabolic syndrome in hamsters." (PMID 27821167, 2016). "THS-exposed mice have ectopic visceral fat accumulation, which is a characteristic of metabolic syndrome and potential problems with insulin signaling because insulin regulates lipid metabolism and storage." (PMID 26934053, 2016). "Glucose intolerance, high levels of serum insulin and blood lipids, larger body masses, and high systolic arterial blood pressures were confirmed in the rat model of metabolic syndrome." (PMID 27006943, 2016). "Insulin is an important regulator of lipid metabolism, and therefore, insulin resistance in the peripheral tissues is a link between metabolic syndrome and dyslipidemia." (PMID 27618093, 2016).
metabolic syndrome (continued). "Our study demonstrated that fasting insulin and HOME-IR was significantly associated with triglyceride levels, one of the criteria used in metabolic syndrome." (PMID 27824069, 2016). "In a rodent study, intake of dietary Salba seed rich in ALA for 3 months reversed the impaired anti-lipolytic action of insulin and dyslipidemia of rats fed a sucrose-rich diet." (PMID 26912161, 2016). "In future studies, we need to confirm that a therapeutic approach to improve insulin sensitivity by such as reductions in visceral fat obesity and ectopic fat deposition can recover vascular dysfunction in metabolic syndrome." (PMID 27188597, 2016). "Insulin is the most important hormone in the metabolic syndrome and its binding with receptors induces inhibition of apoptosis and promotes cell proliferation." (PMID 27029038, 2016). "Amelioration of postprandial dyslipidemia by MGAT2 inhibition is one possible mechanism for improving insulin sensitivity via attenuation of ectopic lipotoxicity in peripheral tissues." (PMID 26938273, 2016). "There are explanations that this leads to unresponsiveness to insulin in the peripheral tissue and subsequently to metabolic syndrome." (PMID 27429613, 2016). "The metabolic syndrome and T2D, fasting serum insulin, body mass index (BMI) and AST/ALT ratio were independent predictors of NAFLD in Chinese." (PMID 27579785, 2016). "We use a large sample of community-dwelling older men to investigate associations between total volume of objectively measured MVPA, LPA and SB with markers of metabolic health; WC, BMI, fat mass index (FMI), fasting serum insulin and metabolic syndrome." (PMID 26980183, 2016). "The skeletal muscle is the predominant site of insulin-stimulated glucose disposal in the postprandial state, and muscle insulin resistance is one of the earliest factors in the pathogenesis of the metabolic syndrome." (PMID 27752300, 2016). "LFC was significantly associated with BMI, all components of metabolic syndrome (waist circumference, blood pressure, serum TG, HDL-c, FBG, and PBG), serum insulin and HbA1c in both male and female subjects (all p <0.05)." (PMID 27284686, 2016). "Insulin plays an important role in lipid synthesis, and liver is the main target organ, thereby possibly altering lipid metabolism and contributing to dyslipidemia." (PMID 26891315, 2016). "Circulating DPP-4 concentrations were increased in obese subjects and correlated with parameters of the metabolic syndrome, such as body mass index, waist circumference, and plasma fasting insulin concentration." (PMID 27652270, 2016). "The subjects studied observed regulation on glucose tolerance, insulin secretion, A1c glycohemoglobin fraction, and dyslipidemia." (PMID 27119007, 2016). "Metabolic syndrome is often linked to chronic inflammation, and because autophagy is downregulated in macrophages by inflammatory stimuli, we wondered whether it plays a role in macrophages and whether there is a link between inflammation and insulin resistance." (PMID 27229537, 2016). "Study objective is to evaluate the efficacy and safety of Insulin sensitizers (metformin and pioglitazone) in psoriasis patients with metabolic syndrome (MS)." (PMID 27531132, 2016). "DFs are implicated in various aspects of metabolic syndromes, such as body weight gain, dyslipidemia, hypertension, insulin sensitivity, and levels of pro- and anti-inflammatory factors." (PMID 27315087, 2016). "Previous studies reported a highly variable proportion of MH people with obesity ranging from 10 to 40% based on varying criteria to define the metabolic syndrome (MetS) and insulin sensitivity." (PMID 27880828, 2016). "IR is a critical characteristic of metabolic syndrome, which is defined as insulin hyporeactivity and reduced absorption and utilization of glucose." (PMID 27733131, 2016). "Low birth weight resulting from salt restriction during pregnancy influences insulin sensitivity and dyslipidemia." (PMID 26787358, 2016).
metabolic syndrome (continued). "When this tissue becomes insulin resistant this will contribute to the development of the metabolic syndrome." (PMID 27166587, 2016). "Adipokines play a significant role in the metabolic syndrome and in cardiovascular diseases, have implications in regulating insulin sensitivity and inflammation, and have significant effects on growth and reproductive function." (PMID 27746590, 2016). "The index patient (body mass index 27 kg/m2) showed elevated fasting glucose and insulin concentrations, increased HbA1c, moderately elevated triglyceride concentrations and dyslipidemia." (PMID 27142837, 2016). "Another clinical trial comparing whole eggs with a yolk-free egg substitute in subjects with metabolic syndrome (MetS) reported superior atherogenic lipoprotein profiles and insulin sensitivity in the group consuming the whole eggs." (PMID 26808174, 2016). "Low serum heptadecanoic acid concentrations were associated with elevated serum concentrations of known markers of metabolic syndrome, including serum ferritin, glucose, insulin and triglycerides in the dolphins." (PMID 27992457, 2016). "The metabolic syndrome should be considered as a clinical diagnosis that is mechanistically driven by a complex combination of factors including impaired fat accumulation, insulin action, and immunity." (PMID 27098727, 2016). "In this regard, and confirming previous results, the present work demonstrates a reversion of dyslipidemia, abnormal glucose homeostasis and whole body peripheral insulin insensitivity when dietary chia seed replaced CO in the SRD-fed rats." (PMID 26828527, 2016). "Elevated peripheral vascular resistance and renal salt retention due to higher sympathetic nervous system activity, angiotensin-aldosterone activity and insulin levels can lead to hypertension in people with adiposity which leads also to dyslipidemia." (PMID 27680100, 2016). "Treatment with BC (100 or 300 mg/kg/day for 8 weeks) significantly suppressed increased liver weight, epididymal fat weight, C-reactive protein (CRP), total bilirubin, leptin, and insulin in rats with induced metabolic syndrome." (PMID 26504474, 2015). "Significantly ameliorated metabolic syndrome by improving peripheral insulin sensitivity and cellular glucose uptake and by modulating the level of circulating lipid metabolites and adiponectin." (PMID 25621503, 2015). "An important link between obesity, metabolic syndrome and dyslipidemia appears to be the impaired ability of insulin to regulate glucose utilization in peripheral tissues." (PMID 25555562, 2015). "When administered at a dose of 1.67 g/kg, TNK improved glucose homeostasis, dyslipidemia and insulin sensitivity in SHR/cp rats." (PMID 25874615, 2015). "Understanding the relationship between BDE-47 and the insulin signaling pathway is expected to have significant impact on the growing population suffering from metabolic syndrome." (PMID 26217518, 2015). "We conducted a series of biometric and plasma measures focusing on adiposity, lipid metabolism, and adipose tissue-derived hormones, which led to a diagnosis of metabolic syndrome in the insulin-resistant animals." (PMID 26063458, 2015). "AKT, mTORC1 and S6K1 are key components of the insulin signaling pathway, which becomes dysregulated in patients with metabolic syndrome." (PMID 25646773, 2015). "Insulin tended to perform better than HOMA-IR in discriminating all the criteria of the metabolic syndrome except for high blood pressure and high glucose, but the latter is linked with HOMA-IR by formula." (PMID 26241903, 2015). "The exact mechanism by which metabolic syndrome develops is not yet fully understood but it appears to be related to insulin resistance and excessive free fatty acid release from intra-abdominal adipocytes." (PMID 26593941, 2015). "It is worthwhile to mention that AOPP levels have been associated with metabolic syndrome, since high levels of AOPP have been positively correlated with insulin and HOMA levels." (PMID 25763281, 2015).
metabolic syndrome (continued). "Diminished tissue sensitivity to insulin is a central feature of various pathological conditions termed the metabolic syndrome (MS)." (PMID 25928697, 2015). "The metabolic syndrome was assessed by measuring the body weight gain, the glucose sensitivity, and the levels of insulin, triglyceride, leptin, and aspartate aminotransferase transaminase (AST) and alanine aminotransferase (ALT)." (PMID 25874022, 2015). "Higher non fasting insulin appears to precede the development of ED and other features of the metabolic syndrome." (PMID 26196519, 2015). "The long-term consequences of metabolic syndrome, high diastolic blood pressure, and elevated insulin level are related to serious sequelae and early death." (PMID 25809098, 2015). "Insulin is an important regulator of lipid metabolism and so insulin resistance within the peripheral tissues is a link between metabolic syndrome and dyslipidemia." (PMID 25889643, 2015). "Failure of the control of glucose levels, with defects in both insulin action and insulin secretion, can result in a metabolic syndrome which is a multisymptom disorder of energy homeostasis." (PMID 25737736, 2015). "Of more importance, peripheral insulin sensitivity (Si) also improved by approximately 20% in individuals with metabolic syndrome consuming the same amount or RS that elicited reductions in blood glucose." (PMID 26703752, 2015). "In patients with metabolic syndrome, the liver becomes selectively resistant to insulin with respect to gluconeogenesis but remains responsive to lipogenesis." (PMID 25646773, 2015). "Recently, an intervention trial reported that a whole-grain cereal-based diet significantly lowers postprandial plasma insulin concentration in individuals with metabolic syndrome." (PMID 26337448, 2015). "Some authors consider hyperuricemia in metabolic syndrome to be the consequence of elevated serum insulin levels, which have been shown to stimulate renal reabsorption of uric acid." (PMID 25763281, 2015). "Metabolic syndrome is a cluster of metabolic abnormalities that occur in persons with impaired insulin sensitivity." (PMID 26030767, 2015). "Changes in body weight, body composition, blood pressure and glucose, insulin and lipid concentrations of participants with metabolic syndrome." (PMID 26024297, 2015). "For metabolic syndrome, the OR of HbA1c was 2.68, of insulin, 11.36, of glucose, 7.03, and of HOMA-IR, 14.40." (PMID 26241903, 2015). "High plasma insulin and glucose levels due to IR are the major components of the metabolic syndrome." (PMID 25668433, 2015). "Per each 10 pmol/L (1.4 uU/mL) increase in insulin, the odds for metabolic syndrome increased by 1.43 (95%CI: 1.38, 1.49)." (PMID 26241903, 2015). "We investigated the role of urokinase plasminogen activator (uPA) and its soluble receptors (suPAR) and plasminogen activator inhibitor-1 (PAI-1) in metabolic syndrome (MetS) components, insulin secretion, and resistance in schoolchildren." (PMID 26633970, 2015). "The present study aimed to investigate the relationship between HNF4A genetic variants and the presence of metabolic syndrome (MetS) in a pediatric French Canadian population, and to explore their association with metabolic parameters, for instance levels of blood glucose, insulin and lipids." (PMID 25671620, 2015). "Nitrate reversed features of metabolic syndrome in eNOS−/− mice, including a reduction in body fat and improved glucose homeostasis and insulin sensitivity." (PMID 26694920, 2015). "Glucose and lipid-lowering drugs and insulin-sensitizing drugs have been widely used in the treatment of metabolic syndrome." (PMID 26652604, 2015). "Nutritional-behavioral interventions can improve the blood lipid profile and insulin sensitivity in obese children, and possibly provide benefits in terms of metabolic syndrome." (PMID 26633492, 2015).
metabolic syndrome (continued). "Insulin sensitivity has been shown to be increased after Ramadan fasting among patients with metabolic syndrome and in patients with type two diabetes mellitus." (PMID 26155596, 2015). "Moxonidine is also shown to exert beneficial effects on a diverse range of metabolic parameters including improvements in indices of glycaemic control, insulin sensitivity, dyslipidemia, and inflammation." (PMID 26064978, 2015). "Similar to humans, common bottlenose dolphins (Tursiops truncatus) can develop subclinical metabolic syndrome, including elevated insulin, triglycerides, glucose, and ferritin, as well as fatty liver disease." (PMID 26200116, 2015). "Obese women had lower insulin sensitivity (P < 0.01), higher plasma sE-selectin (P = 0.007), and higher the metabolic syndrome total Z-score (MS Z-score) (P < 0.0001)." (PMID 23934358, 2014). "In this paper, we have demonstrated dietary effects of cis-9, trans-11 CLA-enriched butter in 60-day-old Wistar rats on feed intake, body composition, insulin and glucose metabolism as well as dyslipidemia." (PMID 25534067, 2014). "Usefulness of a definition inclusive of insulin sensitivity and stricter criteria for metabolic syndrome components as well as the potential addition of markers of fatty liver and inflammation should be explored." (PMID 24400816, 2014). "For this purpose, they have evaluated the relationship between adiponectin concentrations, metabolic syndrome, and insulin sensitivity." (PMID 24587801, 2014). "The baseline hyperphosphorylation of IRS‐1 at Ser337 and Ser636 coincides with the diminished glucose uptake into the muscle in response to increments in blood insulin concentrations in many of the metabolic syndrome subjects." (PMID 25472611, 2014). "The responsiveness of mTOR pathway targets such as p706Sk to a high protein meal containing either dairy or soy foods was investigated in healthy insulin sensitive middle-aged men and those presenting with metabolic syndrome (MetS)." (PMID 25302072, 2014). "Similar enhancement in the first-phase insulin secretion measured by the oral glucose tolerance test (OGTT) was observed in subjects with the features of metabolic syndrome consuming rye bread and pasta daily for 12 weeks." (PMID 25370913, 2014). "Diminished tissue sensitivity to insulin is a characteristic of various pathological conditions termed the insulin resistance syndrome, also known as the metabolic syndrome or cardiometabolic syndrome." (PMID 24485020, 2014). "Resistant starch (RS) is a type of cereal fiber and has been shown to have beneficial effects on insulin sensitivity and fatty acid (FA) metabolism in both healthy individuals and those with metabolic syndrome." (PMID 24671124, 2014). "We have monitored four hallmarks of the metabolic syndrome, namely glucose levels and insulin response, pancreatic islet size as well as ectopic fat accumulation." (PMID 25144618, 2014). "Partial correlation coefficients (R) between bone turnover markers/bone mineral density and fasting insulin/individual characteristics of metabolic syndrome defined by NCEP ATPIII." (PMID 25310090, 2014). "Poor liver health affects many organ systems and impacts multiple arms of the metabolic syndrome, including cardiovascular health, insulin sensitivity, and circulating lipid levels." (PMID 24672550, 2014). "Usefulness of a definition inclusive of insulin sensitivity in concert with stricter criteria for metabolic syndrome components should be explored, as well as the potential inclusion of fatty liver." (PMID 24400816, 2014). "IR is one of the main pathophysiological characteristics of metabolic syndrome, and abnormalities in insulin-glucose metabolism have been repeatedly shown in OSA patients, especially when OSA is severe." (PMID 24466027, 2014).